CRP (C-reactive protein)
Diseases named in the same sentence as CRP in open-access papers (continued):
Sharing a sentence is not in itself a finding about the gene and the disease.
tuberculosis (196 papers, 2009 to 2026). A chronic, recurrent infection caused by the bacterium Mycobacterium tuberculosis. "For example, non-tuberculosis lung infections can simultaneously cause respiratory symptoms, abnormal chest x-ray findings, and elevated C-reactive protein levels." (PMID 41115442, 2025). "Future research is needed to evaluate the diagnostic value of CRP for tuberculosis triaging, specifically combining it with CAD for chest X-ray, symptom screening, or promising biomarkers." (PMID 39190813, 2024). "Associations varied by cause of death: tuberculosis-associated mortality was most strongly associated with higher CRP and sST2, and cryptococcosis-associated mortality with higher IL-4 and lower IL-8." (PMID 38944653, 2024). "Lower TB Score was associated with markers of increased tuberculosis severity including higher semiquantitative bacterial load on Xpert Ultra, lower BMI, and higher C-reactive protein." (PMID 38245113, 2024). "Most evidence on the diagnostic performance of CRP derives from studies in people with HIV as a tuberculosis screen test, while data on symptomatic patients who were screened irrespective of HIV status have only recently been collected." (PMID 39190813, 2024). "A study of US adult patients with cardiovascular diseases also found positive association between BMI and high-sensitive CRP, and another study of Tanzanian adult patients with tuberculosis reported a positive association between BMI and vitamin D." (PMID 36789936, 2023). "CRP is a valuable screening tool and should be added to the tuberculosis screening algorithm to improve diagnostic accuracy of screening for tuberculosis in people living with HIV." (PMID 35806852, 2022). "This study was conducted to determine the diagnostic accuracy of CRP for the detection of tuberculosis in people living with HIV who are positive according to the WHO symptom screen." (PMID 35806852, 2022). "CRP (≥8.25 mg/dL) had a sensitivity of 70.13% and a specificity of 69.86% in predicting tuberculosis, and the total diagnostic accuracy was 70% in the present study." (PMID 35806852, 2022). "Patients in the nursing- and healthcare-associated tuberculosis group had markedly lower levels of serum albumin and hemoglobin, and higher levels of C-reactive protein." (PMID 30423855, 2018). "Previous studies have demonstrated the diagnostic value of CRP in active tuberculosis case detection in otherwise healthy HIV-infected persons, however higher false positive rates were found in passive case detection." (PMID 30107791, 2018). "Multivariable analysis revealed that systemic corticosteroid use, tuberculosis, lymphocytopenia, low serum albumin, and high serum C-reactive protein (CRP) levels were significantly associated with indeterminate QFT-GIT results." (PMID 28732078, 2017). "A prospective evaluation of seven biological markers in patients with different causes for exudative effusions demonstrated that CRP provides the largest AUC (0.92) for distinguishing between parapneumonic effusions and tuberculosis or malignant effusions." (PMID 27194820, 2016). "At baseline,the tuberculosis group had lower serum selenium levels than did the control group.The conversion of bacteriological tests was associated with the CRP/albumin ratioand serum selenium levels 60 days after treatment initiation." (PMID 25029650, 2014). "Gender (p = 0.02), country (p < 0.001), race (p = 0.007), prior tuberculosis (TB) (p < 0.001), hemoglobin (p = 0.008), albumin (p < 0.0001) and log10 CRP (p = 0.006) were significant risk factors for baseline serum selenium deficiency." (PMID 25401501, 2014). "To determine the diagnostic utility of CRP we prospectively evaluated the performance of CRP as a screening test for SNTB in symptomatic ambulatory tuberculosis suspects followed up for 8 weeks in KwaZulu-Natal, South Africa." (PMID 21249220, 2011).
tuberculosis (continued). "At 10% tuberculosis prevalence, these strategies would reduce the number of rapid diagnostic tests needed by 42% for C-reactive protein (≥10 mg/L) and 37% for W4SS then C-reactive protein (≥5 mg/L) compared with W4SS alone, but would miss a similar number of tuberculosis cases." (PMID 34800394, 2022). "Our findings show limitations for CRP and procalcitonin, particularly for discriminiation of tuberculosis form CAP, however they may have greater diagnostic utility as part of a panel of biomarkers or in clinical prediction rules." (PMID 30107791, 2018). "Host and mycobacterial factors are strongly associated with baseline CRP response in tuberculosis." (PMID 27287260, 2016). "However, as the test has low costs and performs unaffected by HIV status, CRP might have potential clinical utility in ruling out tuberculosis in settings or facilities where other diagnostic tests are not available or affordable." (PMID 39190813, 2024). "Nevertheless, we believe that CRP elevation is highly likely due to active tuberculosis as the proportion of participants with CRP >40 mg/L was highest in those with definite (microbiologically confirmed) TBM followed by probable TBM." (PMID 40581751, 2025). "On the 22nd day of anti-tuberculosis therapy, the patient developed right-sided back pain, recurrent fever (38.3°C), and a re-elevated CRP level (7.06 mg/dL)." (PMID 40260365, 2025). "On the 34th day of anti-tuberculosis therapy, the right-sided back pain and fever resolved, and the CRP level improved (2.72 mg/dL)." (PMID 40260365, 2025). "At the outpatient visit on the 113th day of anti-tuberculosis therapy, the CRP level had fully normalized (0.13 mg/dL)." (PMID 40260365, 2025). "The significantly associated factors were bronchoscopic washing, older age, low hemoglobin levels, high CRP levels, and tuberculosis." (PMID 39857029, 2025). "Of the patients, 46.6% tested positive for tuberculosis culture, and 45.1% had elevated CRP levels (≥10 mg/L)." (PMID 39882120, 2024). "This is the first prospective, multicenter simultaneous evaluation and comparison of CAD for digital chest radiography and CRP in patients with presumptive tuberculosis at health facilities in Southern Africa." (PMID 39190813, 2024). "After surgery, we measured the ESR and CRP to evaluate the tuberculosis lesion clearance rate and monitored the recurrence 1 week after surgery and at the last follow-up." (PMID 39741498, 2024). "In this study we investigated the diagnostic performance of 2 potential tuberculosis triage tests, CAD and point-of care CRP testing, in adults presenting with tuberculosis symptoms at health facilities in Southern Africa." (PMID 39190813, 2024). "In decision curve analysis, Suliman4 and CRP had similar clinical utility to guide confirmatory tuberculosis testing, but both had higher net benefit than W4SS." (PMID 38583459, 2024). "Controversially, few studies have demonstrated that ESR and CRP are sensitive markers for tuberculosis." (PMID 39582970, 2024). "The WHO also conditionally recommends screening for tuberculosis with C-reactive protein (CRP) in people with human immunodeficiency virus (HIV)." (PMID 39190813, 2024). "Some studies have demonstrated that CRP increased in tuberculosis patients, and these levels declined with the progress of treatment." (PMID 38803498, 2024). "In settings where tuberculosis is prevalent, the ADA/CRP ratio serves as a cost-effective and accessible diagnostic tool, augmenting clinicians' ability to diagnose and manage tubercular effusions effectively." (PMID 39205740, 2024). "C-reactive protein (CRP)-based tuberculosis (TB) screening is recommended for people with HIV (PWH)." (PMID 38712173, 2024). "Accuracy of point-of-care C-reactive protein for tuberculosis among children according to microbiological (MRS) and composite reference standards (CRS)." (PMID 39446791, 2024).
tuberculosis (continued). "Apart from serum proteins other proteins such as C-reactive protein, procalcitonin, and serum amyloid A also provide important information about the severity of tuberculosis." (PMID 37791165, 2023). "There are some features in the model that are not in the diagnostic criteria but are also meaningful for the diagnosis of tuberculosis, such as erythrocyte sedimentation rate and C-reactive protein." (PMID 36927471, 2023). "Continuous CRP values are useful in assessing the response of abdominal tuberculosis to anti-tuberculosis therapy." (PMID 37641023, 2023). "Erythrocyte sedimentation (ESR) and C-reactive protein (CRP) concentrations were detected to assess tuberculosis activity." (PMID 37626361, 2023). "There was a statistically significant relationship between the CRP value and tuberculosis positivity (p value < 0.001)." (PMID 35806852, 2022). "CRP is an acute phase reactant, the levels of which rise in response to IL-6 mediated pyogenic infections such as active tuberculosis." (PMID 35806852, 2022). "There was a statistically significant relationship between the ideal CRP value and tuberculosis positivity (p value < 0.001)." (PMID 35806852, 2022). "From our study, the relationship between being CRP-positive (with a cut-off value of 10 mg/L) and tuberculosis was found to be statistically significant." (PMID 35806852, 2022). "CRP had fair validity in predicting tuberculosis, as indicated by an area under the curve of 0.777 (95% CI 0.703 to 0.851, p value < 0.001)." (PMID 35806852, 2022). "We found that there was a statistically significant relationship between CRP and tuberculosis positivity (p value < 0.001)." (PMID 35806852, 2022). "CRP has been proposed to be a potential biomarker for tuberculosis disease as well as a prognostic indicator of disease and treatment." (PMID 35806852, 2022). "Out of the 77 participants with tuberculosis, CRP was found to be positive in 50 (64.94%) individuals and negative for 27 (35.06%)." (PMID 35806852, 2022). "Out of 150 participants, 67 (44.67%) were found to be CRP-positive, and a total of 77 (51.33%) were tuberculosis-positive." (PMID 35806852, 2022). "From this study, it was concluded that the relationship between CRP-positive (with a cut-off value of 10 mg/L) and tuberculosis was found to be statistically significant." (PMID 35806852, 2022). "C-reactive protein levels in the blood were measured, and the patients were followed up with for a confirmatory diagnosis of tuberculosis." (PMID 35806852, 2022). "The current WHO-consolidated guidelines on tuberculosis include CRP as a screening tool for tuberculosis in treatment-naïve individuals with HIV as a conditional recommendation." (PMID 35806852, 2022). "Tuberculosis and malaria infection status and serum C-reactive protein levels were also similar between groups." (PMID 36684996, 2022). "The high specificity of C-reactive protein would reduce the time to start tuberculosis preventive therapy in people living with HIV." (PMID 34800394, 2022). "In multidrug-resistant tuberculosis, ESR and CRP were as high as 62.03 mm/h and 83.24 mg/L, respectively, which were significantly higher than the ESR (37.20 mm/h) and CRP (50.02 mg/L) levels in drug-susceptible tuberculosis." (PMID 35633888, 2022). "We also found that the highest significant trends and lower levels of CRP and IP-10 were observed in the two-month treated tuberculosis (TB) patients." (PMID 34206598, 2021). "Old tuberculosis (Old Tb) was more frequent (p = 0.0373) and C-reactive protein (CRP) were higher (p = 0.0004) in the alternative regimen group." (PMID 33441977, 2021). "Currently, CRP is the only available inexpensive POC-compatible investigation with the potential to be a suitable triage test for tuberculosis." (PMID 34252128, 2021).
tuberculosis (continued). "Adenosine deaminase (ADA), erythrocyte sedimentation rate (ESR), high-sensitivity C-reactive protein (hs-CRP), tuberculosis antibody (TB-Ab), and cancer antigen 125 (CA125) are commonly used for the diagnosis of TB." (PMID 32256565, 2020). "In the present study, CRP levels were high, this finding was similar to those of other studies conducted in Korea and Brazil on patients with tuberculosis." (PMID 31877169, 2019). "CRP cut-offs with reasonable diagnostic accuracy were found for PJP versus CAP, PJP versus tuberculosis and PJP versus the other two infections." (PMID 30107791, 2018). "Elevated CRP concentrations (> 10 mg/L) were found in 206/210 (98%) participants: 131/133 (98%) with tuberculosis, 60/61 (99%) with CAP, and 15/16 (94%) with PJP." (PMID 30107791, 2018). "Although the specificity of CRP and ESR are low to diagnose tuberculosis, we should emphasize their diagnostic value." (PMID 26823075, 2016). "More recently, some studies have reported the association between sputum conversion at 60 day of TB treatment with decreases in serum levels of CRP, CXCL10, IL-17, MMP-8, as well as with cytokine responses after M. tuberculosis-specific in vitro stimulation of peripheral blood." (PMID 27494953, 2016). "The serum C-reactive protein (CRP) concentration is commonly measured during the investigation or treatment of active Tuberculosis (TB)." (PMID 27287260, 2016). "CRP was especially emphasized to be a good marker for indicating a response to the anti-tuberculosis treatment." (PMID 26823075, 2016). "BMI and total cholesterol were significantly higher in the control group, whereas the total protein, ALP, and CRP were significantly higher in the tuberculosis group (p < 0.05)." (PMID 26197334, 2015). "ESR and CRP, which will initially be elevated significantly, and normalize over time on therapy, in patients with active tuberculosis have been used to predict disease severity and curative effects for several decades." (PMID 26243259, 2015). "Noteworthy low levels of vitamin A, correlating with reduced TTR and raised concentrations of C-reactive protein, have been reported in patients with tuberculosis." (PMID 23270597, 2012). "Based on proteomic fingerprinting of serum Agranoff and colleagues proposed a rapid screening test for active tuberculosis based on the measurement of inflammation parameters including C-reactive protein, transthyretin, serum amyloid A, and neopterin." (PMID 23185397, 2012). "IDO-1 expression in infected mouse lungs has been reported, and elevated IDO-1 expression has recently been correlated with the expression of other inflammatory markers, including C-reactive protein and poor prognosis of tuberculosis patients." (PMID 22649518, 2012). "Within tuberculosis patients the BMI and leptin levels were positively correlated and decreased with increasing disease severity, whereas higher concentrations of IL-6, CRP, IL-1β, cortisol, and ghrelin were seen in cases with moderate to severe tuberculosis." (PMID 22022605, 2011). "Group classification by means of discriminant analysis and the k-nearest neighbor method showed that tuberculosis patients were clearly different from the other groups, having higher levels of CRP and lower DHEA concentration and BMI." (PMID 22022605, 2011). "We have shown that CRP has high sensitivity for the diagnosis of tuberculosis in this well-defined ambulatory cohort of SNTB suspects." (PMID 21249220, 2011). "Our study is unique and the first to report changes in acute phase reactants (albumin, CRP, and beta-2-microglobulin) as measures of inflammation and how their levels relate to repletion of body composition components during treatment of tuberculosis." (PMID 22567264, 2011). "The median CRP quotient in the confirmed tuberculosis group was 15.4 (IQR 7.2; 23.3), 5.8 (IQR 1.4; 16.0) in the group with possible tuberculosis, and 0.7 (IQR 0.2; 2.2) in the group without tuberculosis (p<0.0001)." (PMID 21249220, 2011).
tuberculosis (continued). "The utility of CRP in the diagnosis of SNTB should be evaluated in other primary care settings in sub-Saharan Africa where the prevalence of tuberculosis and/or HIV is lower." (PMID 21249220, 2011). "CSF: cerebrospinal fluid, MTB/RIF: Mycobacterium tuberculosis/rifampicin, PCR: polymerase chain reaction, HIV: human immunodeficiency virus, TPHA: Treponema pallidum hemagglutination assay, VDRL: Venereal Disease Research Laboratory, TB: tuberculosis, CRP: C-reactive protein." (PMID 41523506, 2025). "The results of our study disqualify CRP as a stand-alone triage for tuberculosis." (PMID 39190813, 2024). "The role of CRP in tuberculosis triage requires further research." (PMID 39190813, 2024). "Tuberculosis being an infectious disease, C reactive protein may also increase, but for different types of tuberculosis in different stages of disease, the C reactive protein manifestation needs further study." (PMID 36927471, 2023). "Given that neutrophilic tuberculous effusion is associated with severe inflammation, serum biomarkers representing inflammation such as lactate dehydrogenase (LD), C-reactive protein (CRP), and white blood cells (WBCs) have been associated with the different stages of tuberculosis." (PMID 37864205, 2023). "In addition to guiding the use of antibiotics around the world to tackle the growing AMR crisis, CRP has recently also been recommended by the World Health Organization (WHO) as a screening tool for tuberculosis (TB)." (PMID 36662693, 2023). "However, even at this high sensitivity, the W4SS and CRP concentration would miss roughly one in 50 tuberculosis cases." (PMID 35338834, 2022). "CRP had a sensitivity of 64.94% (95% CI 53.22% to 75.47%) in predicting the presence of tuberculosis, a specificity of 76.71% (95 CI 65.35% to 85.81%), a false-positive rate of 23.29% (95 CI 14.19% to 34.65%), and a false-negative rate of 35.06% (95 CI 24.53% to 46.78%)." (PMID 35806852, 2022). "In this study, after ROC analysis of the data, we found that a CRP value of 8.25 mg/dL which provided optimum sensitivity and specificity, had fair predictive validity in detecting tuberculosis, as indicated by an area under the curve value of 0.777 (95% CI 0.703 to 0.851, p value < 0.001)." (PMID 35806852, 2022). "We analyzed the correlations between TB Ag-Nil and WBC, ESR, CRP and disease duration in 51 tuberculosis patients and 72 non-tuberculosis patients in our sample and found that TB Ag-Nil was significantly positively correlated with patient course in the tuberculosis group." (PMID 36204647, 2022). "Sensitivity and specificity of CRP in the diagnosis of culture-positive tuberculosis." (PMID 34252128, 2021). "The high value of CRP is possibly indicative of developing cardiovascular disease, active inflammation, bacterial infection, and inflammatory bowel disease, and other similar conditions like intestinal lymphoma and tuberculosis." (PMID 32664977, 2020). "We found cut-offs with sensitivities of 90% or more for CRP for all three target infection pairs, and for procalcitonin for two target infection pairs (tuberculosis versus PJP and CAP versus PJP), but specificities were much lower than the 70% recommended by WHO for tuberculosis screening tests." (PMID 30107791, 2018). "CRP and procalcitonin showed limited value in discriminating between the three target infections due to widely overlapping distributions, but diagnostic accuracy was higher for discriminating PJP from CAP or tuberculosis." (PMID 30107791, 2018). "Our participants with mixed infection had higher median concentrations of both CRP and procalcitonin than the participants with tuberculosis and PJP as single infections, but statistical significance was only found when comparing mixed infection to PJP as a single infection." (PMID 30107791, 2018).